MPZ (myelin protein zero)
Diseases named in the same sentence as MPZ in open-access papers (continued):
Sharing a sentence is not in itself a finding about the gene and the disease.
neuromyotonia (1 paper, 2025). "Given the role of axo-glial interactions in stabilizing nodes and paranodes, one could hypothesize that certain CMT2-related MPZ mutations, like in our patients, could cause nerve membrane hyperexcitability which leads to the phenomenon of neuromyotonia." (PMID 40009145, 2025).
polyneuropathy (1 paper, 2013). A disease or disorder affecting more than one nerve. "Genetic testing was performed according to polyneuropathy type; demyelinating/mixed: PMP22 duplication, MPZ, EGR2, LITAF, NEFL, PMP22, GJB1, axonal: MFN2, MPZ, NEFL, and GJB1." (PMID 24053775, 2013).
relapsing remitting MS (1 paper, 2016). "We herein report a case of Charcot‐Marie‐Tooth disease type 1B with p.Val102fs mutation in the MPZ gene that developed relapsing remitting MS." (PMID 28032003, 2016).
schizophrenia (1 paper, 2015). A major psychotic disorder characterized by abnormalities in the perception or expression of reality. "For example, MPZ encodes a major structural protein of peripheral myelin, and an increasing number of evidence supported myelin-related protein and pathways contribute to the risk of schizophrenia and other psychiatry disorders." (PMID 26674772, 2015).
scoliosis (1 paper, 2023). A congenital or acquired spinal deformity characterized by lateral curvature of the spine. "Although most were associated with classic demyelinating phenotypes (55/75, 73.3%), there was considerable phenotypic heterogeneity such as prominent deep sensory disturbances (SH3TC2, PRX) and scoliosis (SH3TC2, MPZ, and PMP22)." (PMID 37519884, 2023).
ZIKV infection (1 paper, 2018). "Peripheral DRG neurons were visualized by neurofilament-H (NF-H) staining, whereas myelin protein zero (P0) was used to identify myelinating SC and ZIKV infection was revealed by anti-viral envelope (E) protein monoclonal Ab (mAb)." (PMID 29976926, 2018).
peripheral neuropathies (9 papers, 2012 to 2025). "Pathogenic variants in the MPZ gene are associated with a broad spectrum of inherited peripheral neuropathies, primarily characterized by progressive muscle weakness, atrophy, and sensory loss." (PMID 41363019, 2025). "Charcot–Marie–Tooth type 1B (CMT1B) is a peripheral neuropathy caused by mutations in the gene encoding myelin protein zero (MPZ), a key component of the myelin sheath in Schwann cells." (PMID 39273178, 2024). "We assessed 77 patients with inherited peripheral neuropathy comprising 64 with reported MPZ variants and 13 with novel pathogenic MPZ variants." (PMID 33179255, 2021). "In 1657 Japanese patients with suspected inherited peripheral neuropathy, we identified 23 known and 17 novel MPZ variants in 85 unrelated patients." (PMID 33179255, 2021). "We confirmed 23 previously reported variants in MPZ gene from 64 patients with inherited peripheral neuropathy from different families." (PMID 33179255, 2021). "In this study, we investigated six probands with inherited peripheral neuropathies associated with MPZ variants, who visited a single medical center." (PMID 34925207, 2021). "In some peripheral neuropathies such as CMT Type 1A, Schwann cell disruption by mutations in peripheral myelin protein 22 (PMP22) or myelin protein zero (MPZ) cause secondary axon degeneration." (PMID 37614471, 2023). "Although immortalized cell lines stably or transiently expressing various MPZ mutations have been utilized to study CMT1B, researchers are increasingly adopting DRG explant or DRG/Schwann cell co-cultures as a more physiologically relevant system for investigating peripheral neuropathy." (PMID 39273178, 2024). "CNV in the MPZ gene have been reported as the cause of inherited peripheral neuropathy, however, none of the patient were confirmed with CNV in MPZ gene in the preset study." (PMID 33179255, 2021).
tumor (8 papers, 2022 to 2025). "Another study identified significant communication between MCs and a subset of myofibroblasts, potentially promoting tumor growth, invasion, and metastasis through the myelin protein zero (MPZ) signaling network." (PMID 41035074, 2025). "Through an exploration of cellular interactions, we discovered that the MPZ signaling pathway network exhibits substantial cellular interactions in crucial subpopulations of Myofibroblasts and tumor cells, with the gene MPZL1 identified as a key player." (PMID 38562930, 2024). "Intriguingly, these cells exhibit a high degree of interaction with tumor cells through the MPZ signaling pathway network, suggesting that Myofibroblasts may facilitate tumor progression via this pathway." (PMID 38562930, 2024). "Simultaneously, there was a significant upregulation of MPZ and COL1A1 levels and a decrease in Ki‐67 levels in the tumor tissue treated with recombinant mRNA, demonstrating the acquisition of Schwann cell‐like characteristics within the tumor." (PMID 38973154, 2024). "IHC analysis of xenografted tumour tissues revealed that MPZ, SCARA3, MPP2 and PBXIP1 expression levels were low in the SW620/sh-MPZ, SW620/sh-SCARA3, SW620/sh-MPP2 and SW620/sh-PBXIP1 groups." (PMID 36117173, 2022). "Finally, experimental validation revealed that the knockout of the key gene within the MPZ pathway, MPZL1, can inhibit tumor activity, proliferation, invasion, and migration capabilities." (PMID 38562930, 2024). "Although not a direct target of de novo enhancers, MPZ was also upregulated upon EWSR1-ATF1 depletion in CCS tumor cells." (PMID 35477713, 2022).
cancer (6 papers, 2017 to 2025). A tumor composed of atypical neoplastic, often pleomorphic cells that invade other tissues. "The immunostaining of MPZ reveals the characteristic shape of the nerve fibers which changes in agreement with its increased then decreased expression with the development of malignant tumors." (PMID 39050471, 2024). "Gene ontology (GO) analysis revealed that MPZ+ mSCs were significantly enriched in neuron apoptosis processes, neuron death, and tumor necrosis factor-mediated signaling pathways, possibly reflecting the damage response induced by cancer cell invasion." (PMID 40148311, 2025). "Among these clusters, MPZ+ mSCs (cluster 0), PMP22+ mSCs (cluster 1), and SCPs (cluster 4) were predominantly located in cancer-adjacent tissues." (PMID 40148311, 2025). "For cell–cell contacts, CD99, MPZ and THY1 were the common cellular interaction media in most cancers." (PMID 36772945, 2023). "For unreported model genes (MPZ, SCARA3, MPP2 and PBXIP1), recent studies have demonstrated that those genes are involved in the development of cancers." (PMID 36117173, 2022).
hereditary peripheral neuropathy (2 papers, 2023 to 2024). An instance of peripheral neuropathy that is caused by an inherited genomic modification in an individual. "Mutations in myelin protein zero (MPZ) cause the hereditary peripheral neuropathy Charcot Marie Tooth 1B." (PMID 38320810, 2024).
genetic disorder (1 paper, 2014). "CMT2 is a highly heterogeneous genetic disorder but 4 genes are the most frequently involved : the GJB1 (connexin-32), MPZ (P0 or myelin protein-zero), MFN2 (mitofusin 2) and GDAP1 (ganglioside-induced differenciation-associated protein 1)." (PMID 24804794, 2014).
infection (1 paper, 2022). The state of being infected such as from the introduction of a foreign agent such as serum, vaccine, antigenic substance or organism. "In contrast, PIC treatment notably decreased MPZ gene expression at 6 h post infection compared to untreated cells (two-fold decrease, p < 0.01)." (PMID 36611893, 2022). "M. leprae was shown to infect and persist in SC and subsequent infection promoted dedifferentiation of host SC into progenitor stem-like cells with a marked downregulation of myelin genes (MPZ, MBP, and Erg2) and a reduced remyelination capacity in infected SC." (PMID 36611893, 2022).
neurogenetic diseases (1 paper, 2021). "Both novel variants were not seen in healthy individuals with no known history of neurogenetic diseases or in multiple databases, which further suggested that c.67+4A>G and p.A27fs are disease-causing rather than normal variants of MPZ." (PMID 34925207, 2021).
neurological disease (1 paper, 2010). "Specifically, we performed targeted genomic re-sequencing of a collection of patients with neurological disease, focusing our attention on predicted SOX10- and EGR2-binding sites within evolutionarily conserved non-coding regions of the MPZ gene." (PMID 21179557, 2010).
MPZ also shares sentences with these, for which no sentence is quoted: chronic inflammatory demyelinating polyneuropathy (2 papers); and sensory neuropathy (1); Ataxia (1); bladder cancer (1); Charcot Marie Tooth neuropathy (1); Charcot-Marie-Tooth disease type 1A (1); Charcot-Marie-Tooth type 2 (1); clear cell renal cell carcinoma (1); colorectal tumour (1); Dejerine-Sottas disease (1); distal limb muscle atrophy (1); epilepsy (1); Holmes-Adie syndrome (1); Hyperglycemia (1); liver cancer (1); Miosis (1); Mydriasis (1); myopathy (1); neurodegenerative disease (1); Pelizaeus-Merzbacher disease (1); peripheral nerve injury (1); psoriasis (1); Treacher-Collins syndrome (1); trigonocephaly (1).